FDX1 (ferredoxin 1)
Diseases named in the same sentence as FDX1 in open-access papers (continued):
Sharing a sentence is not in itself a finding about the gene and the disease.
tumor (continued). "By TCGA pan-cancer expression analysis, we observed that FDX1 was heterogeneously expressed in a multitude of neoplasms and markedly downregulated in tumor tissues of KIRC." (PMID 36212447, 2022). "According to our results, knockdown of FDX1 promoted the proliferation of tumor cell lines, verifying the inhibitory effect of FDX1 in those tumors." (PMID 36226187, 2022). "Third, the effects of FDX1 on the tumor microenvironment and immunotherapy required experimental and clinical validation." (PMID 36210836, 2022). "The results in TCGA database showed that the expression of FDX1 was statistically correlated with tumor grade and 1p19q codeletion." (PMID 36523779, 2022). "In summary, our first pan-cancer analysis of FDX1 indicated that this factor was differentially expressed between tumor and normal tissues and revealed correlations between FDX1 expression and DNA methylation and RNA methylation-related genes." (PMID 36210836, 2022). "ATP7A (P = 0.008), COA6 (P = 0.016), TMEM199 (P = 0.024) and FDX1 (P = 0.004) expression were significantly related to tumor stage (T classification)." (PMID 36313717, 2022). "In agreeance with the outcomes of database analysis, FDX1 was significantly hyper expressed in the normal kidney while weakly expressed in the tumor." (PMID 36212447, 2022). "We also assessed the relationship between FDX1 expression and DNA methylation, microsatellite instability (MSI), tumor mutation burden (TMB), and tumor microenvironment (TME) in pan-cancer." (PMID 36210836, 2022). "Subsequently, we revealed that the expression of FDX1 was highly correlated with gender, histological tumor grade, and pathological tumor stage, thus revealing that low FDX1 expression had a strong relationship with a malignant ccRCC phenotype." (PMID 36292610, 2022). "ATP7A expression was significantly higher in tumor tissues than in paraneoplastic tissues, while FDX1, DBT, and LIAS expression was significantly lower than in paraneoplastic tissues (P<0.05)." (PMID 36568224, 2022). "We then verified FDX1 protein expression by immunoblotting assay with nine pairs of tumours and adjacent tissues and by IHC in tissue microarrays with 199 pairs of tissues." (PMID 36186457, 2022). "Malignant cells in BRCA, GBM, MCC, PAAD, and SKCM obtained a stronger FDX1 expression ability than other tumor types." (PMID 36605188, 2022). "PPD/PDP@si-FDX1 demonstrated pH/ROS-responsive tumor accumulation and enhanced si-FDX1 delivery." (PMID 42026685, 2026). "Also, the overexpression of FDX1 in ccRCC cell lines suppressed tumor growth and strengthened the immune response against the tumor by enhancing the secretion of the TNFγ and IL-2." (PMID 41198664, 2025). "Similarly, FDX1 acts as a tumor suppressor role in ccRCC, in silico approaches implies that it can be a great prognostic marker and highly correlate with immune infiltration in ccRCC." (PMID 41198664, 2025). "While the study of it is mainly focused on tumor therapy, in the present study, two key cuproptosis-related genes, ferredoxin (FDX1) and dihydrolipoamide S-acetyltransferase (DLAT) homologs (designated as CgFDX1 and CgDLAT), were identified from Crassostrea gigas." (PMID 39936990, 2025). "In multivariate analysis, after adjusting for age, gender, TNM stage, histological grade, and residual tumor status, FDX1 remained an independent prognostic factor for overall survival (HR = 0.825, 95% CI 0.546–1.246, p = 0.360), though the statistical significance was attenuated." (PMID 40410601, 2025). "Additionally, the pH‐responsive and photothermal properties of MIL‐Cu1.8S‐TPP/FA facilitated the controlled release of iron and copper ions, triggering ferroptosis and cuproptosis via GSH depletion, GPX4 inactivation, and FDX‐1 downregulation in tumor cells." (PMID 40558386, 2025).
tumor (continued). "In this study, we further validated the low-expression characteristic of FDX1 in ccRCC, and its reduced expression could predict adverse tumor pathological conditions and shorter OS and DFS of patients." (PMID 40118855, 2025). "Similarly, we found that Elesclomol pulse treatment in vivo significantly inhibited OC tumor growth and increased FDX1 expression within the tumor." (PMID 40119652, 2025). "Moreover, our in vitro and in vivo experiments have fully validated the inhibitory effects of FDX1 overexpression on the proliferation and metastasis of ccRCC cells, indicating its role as a tumor suppressor gene in ccRCC." (PMID 40118855, 2025). "A deeper understanding of the interplay between FDX1 and cuproptosis may foster the development of more effective and safer anti-tumor therapies, particularly for challenging malignancies where cuproptosis mechanisms could offer novel treatment options." (PMID 40406488, 2025). "This pattern suggests that tumors with high FDX1 expression may exhibit a less favorable immune microenvironment, potentially limiting immune-mediated tumor suppression." (PMID 40410601, 2025). "Similarly, FDX1 downregulation promotes tumor progression through coordinated activation of mitophagy and PI3K/AKT signaling linked to excessive ROS production in HCC." (PMID 41573680, 2025). "Ferredoxin-1 (FDX1) inhibition has been associated with increased CD8+ T cell infiltration and a reduction in immunosuppressive cell populations in the TME, thereby enhancing anti-tumor immunity." (PMID 40872475, 2025). "Thus, further exploration of the relationship between the regulation of FMR1 by FDX1 and the tumor immune microenvironment will contribute to a deeper understanding of tumor immunotherapy." (PMID 40118855, 2025). "Interestingly, FDX1 expression varies across different tumor types, and high expression of FDX1 is predicted to correlate with improved patient prognosis." (PMID 40244269, 2025). "Additionally, in vivo experiments employing the xenograft model demonstrated that GPRIN2 depletion increased tumor growth and tumor weight, while FDX1 overexpression decreased both." (PMID 38802900, 2024). "Targeting Ferredoxin 1-mediated metabolic vulnerabilities could offer novel strategies to selectively inhibit tumor growth while sparing normal cells, thereby improving the efficacy of cancer treatment and overcoming therapeutic resistance." (PMID 38802900, 2024). "To examine if the Fdx1+/- +/- were tumor-prone, we performed histological analysis." (PMID 38251655, 2024). "We grouped the cells into 25 clusters and divided the cell clusters into 8 types based on annotation, which are: endothelial cells, FDX1 + tumor/epithelial cells, fibroblasts, lymphocytes, macrophages, smooth muscle cells, tumor/epithelial cells (other types), and VEGFA + tumor/epithelial cells." (PMID 38200479, 2024). "ES-Cu-MOF nanoparticles could lead to the depletion of the FDX1 and an augmented production of mitochondrial ROS, both of which were consequences of the cuproptosis of tumor cells." (PMID 38938647, 2024). "Another study made clear that FDX1 has a unique expression pattern across various cancers and it might be a potential predictor of treatment effects for tumor patients." (PMID 39329964, 2024). "Our results suggest that VEGFA + tumor/epithelial cells and FDX1 + tumor/epithelial cells may play irreplaceable roles in the tumor immune microenvironment." (PMID 38200479, 2024). "Moreover, the impact of FDX1 on tumorigenic ability was investigated in a xenograft model, demonstrating that FDX1 overexpression in A549 cells led to significant decreases in tumor growth and tumor weight in nude mice." (PMID 38802900, 2024). "Tumor cell viability in the low-FDX1 group was higher than that in the high-FDX1 group." (PMID 37361595, 2023). "Therefore, the level of FDX1 expression is relatively differentially expressed in healthy and tumor tissues, making it an ideal target for tumor-specific silencing." (PMID 37298135, 2023).
tumor (continued). "Finally, the effect of FDX1 expression on the tumor microenvironment was predicted, and clinical samples were examined by flow cytometry to confirm our prediction." (PMID 36173462, 2023). "FDX1 plays a role in inducing cuproptosis and modulating tumor immunity, which could be considered as potential therapeutic targets in COAD." (PMID 36173462, 2023). "Moreover, the survival prognosis, clinical features, methylation, and biological functions of FDX1 were evaluated, and the tumor immune dysfunction and exclusion (TIDE) score was used to explore the immunotherapy response to FDX1 in ccRCC." (PMID 37432054, 2023). "Moreover, high expression of FDX1 suggests a good prognosis and immune cell infiltration, which can effectively inhibit tumor cell invasion and metastasis." (PMID 36173462, 2023). "Some genes were more different in tumor samples (FDX1; Dihydrolipoamide Dehydrogenase, DLD)." (PMID 37239416, 2023). "There was a significant correlation between FDX1 and immune infiltration in tumor samples of KIRC." (PMID 36755576, 2023). "To explore whether cuproptosis is related to the tumor immune microenvironment, we explored the correlation of cuproptosis core protein FDX1 with immunity." (PMID 36825202, 2023). "FDX1 participates in cuproptosis, a copper-dependent cell death mode, which might influence tumor progressions like ferroptosis and pyroptosis." (PMID 36825202, 2023). "We inferred that FDX1 may participate in the interaction between tumor cells and endothelial cells, mediate the damage of endothelial cell barrier, and thus lead to tumor invasion and metastasis." (PMID 36755576, 2023). "The mRNA level of FDX1 was lower in tumor tissue in the GSE167573 and TCGA-KIRC cohorts." (PMID 36766692, 2023). "Conversely, the underexpression of genes like PEBP1, NAPSA, and FDX1 in ccRCC may indicate their roles as tumor suppressors or regulators of critical cellular processes." (PMID 37985807, 2023). "FDX1 plays a critical role in tumor occurrence, development, prognosis, and treatment." (PMID 37432054, 2023). "Therefore, we performed a pan-cancer analysis of FDX1 using multiple databases to evaluate the features of gene expression, prognosis, and tumor immunity." (PMID 37193786, 2023). "In addition, FDX1 overexpression restrained ccRCC cell line malignancy and enhanced tumor immunity by increasing the secretion levels of IL2 and TNFγ." (PMID 36766692, 2023). "Involvement of FDX1 in the tumor immune microenvironment depends on tumor types." (PMID 36825202, 2023). "From this, we speculate FDX1 may be involved in the metabolic disorder during the occurrence and development of cancer, subsequently changing its phenotype and tumor microenvironment." (PMID 36925927, 2023). "Dysregulated FDX1 in ccRCC could promote tumor progression through metabolic reprogramming and carcinogenic pathways, such as fatty acid metabolism, PI3K-AKT-mTOR signaling, and the Myc pathway." (PMID 36766692, 2023). "FDX1 is known as an important regulatory factor in cuproptosis, however, its roles in tumor pathogenesis and immune infiltration remain unclear." (PMID 37193786, 2023). "FDX1 was also participated in immune regulation and the tumor microenvironment." (PMID 37193786, 2023). "FDX1 acted as a biomarker for elesclomol due to the FDX1 activity and promoted mitochondria-dependent energy metabolism inducing the toxic effect of elesclomol in tumor cells." (PMID 36825202, 2023). "We found that FDX1 was low expressed in KIRC tumor tissues and may be an independent prognostic gene of KIRC." (PMID 36755576, 2023). "FDX1 expression was detected in tumor samples of these cases using real-time PCR." (PMID 37361595, 2023). "All these results reminded us that restoration of FDX1 normal expression levels in ccRCC could enhance tumor immunity and hamper the malignancy of ccRCC." (PMID 36766692, 2023).
tumor (continued). "In addition, other studies have demonstrated that high FDX1 expression can contribute to a variety of biochemical metabolic pathways that can impact tumor development and progression." (PMID 37298135, 2023). "Combined with these results, our study indicated that FDX1 might be a target of chemotherapeutic drugs or molecular mechanisms of tumor resistance." (PMID 36766692, 2023). "In addition, the expression level of FDX1 was downregulated with tumor progression, including TNM, stage, and grade systems." (PMID 36766692, 2023). "In addition, tumor stemness correlation analysis suggested that FDX1 expression was correlated to stemness score across multiple tumor types." (PMID 36825202, 2023). "Differential expression of FDX1 in tumor stages was performed on GEPIA2.0." (PMID 36825202, 2023). "Finally, in vivo experiments were utilized to decipher FDX1 in ccRCC malignancy and its role in tumor immunity." (PMID 36766692, 2023). "In addition, the expression of FDX1 in tumors was lower than that in adjacent tumor samples from TCGA (KIRC), International Cancer Genome Consortium (ICGC) (RECA-EU), Gene Expression Omnibus (GEO) (GSE66272), and ArrayExpress (E-MTAB-3267) databases." (PMID 37432054, 2023). "Therefore, we used multiple databases, such as TCGA and cBioPortal, to analyze CDRs and FDX1 expression aberrance, genomic alteration, biological function, and tumor immunity across different types of tumors." (PMID 36766692, 2023). "In this section, we aimed to decipher the role of FDX1 in ccRCC tumor immunity." (PMID 36766692, 2023). "FDX1 played a protective role in ccRCC, and its expression level was significantly decreased in tumor tissues, which might be regulated via CNV events." (PMID 36766692, 2023). "Several other studies have found that FDX1 and DLAT are associated with tumor progression." (PMID 37745716, 2023). "We therefore speculate that FDX1 might be used as one of the markers of immune status to predict tumor immunotherapy response." (PMID 36825202, 2023). "Some studies revealed that FDX1 can regulate protein lipoylation modification, and high expression of lipoylated protein may become a new direction of tumor therapy." (PMID 36755576, 2023). "Thus, change of tumor immune microenvironment was one of the main reasons of survival difference in patients with LIHC with a low/high FDX1 expression." (PMID 37361595, 2023). "Then whether cuproptosis also was one of the main reasons in survival improvement of LIHC with a high FDX1 expression, we detected viability of tumor cells from LIHC cases with a low/high FDX1 expression." (PMID 37361595, 2023). "Growing evidence also shows that FDX1 affects tumor development." (PMID 36210836, 2022). "Supporting that, FDX1 also plays a vital role in glucose metabolism, promoting tumor progression." (PMID 36210836, 2022). "Lower expression of FDX1 in the CRGPI-high subgroup may be the reason because of less copper-induced tumor cell death, consistent with our previous FDX1 survival results." (PMID 36177029, 2022). "To determine whether cuproptosis has an effect on the immune environment of tumors, we explored the link between FDX1 expression and immune infiltration in each tumor." (PMID 36226187, 2022). "To pursue the clinical value of FDX1 in ccRCC, we first correlated the FDX1 IHC intensity with the histological T stage and tumor grade of ccRCC tumors in the micro-array (n = 51, we excluded 11 tumors because their T stage and grade were not confidently confirmed by a pathologist)." (PMID 36611966, 2022). "Immunoblotting revealed pervasive downregulation of FDX1 expression in primary tumour lesions." (PMID 36186457, 2022). "In addition, several studies have highlighted the tumor-suppressing role of FDX1 in ccRCC development." (PMID 36611966, 2022).
tumor (continued). "Finally, the relationship between FDX1 and immunotherapy response was further explored through Gene Set Enrichment Analysis enrichment analysis, tumor microenvironment, immune cell infiltration, immune gene co-expression and drug sensitivity analysis." (PMID 35991547, 2022). "Finally, the wounding healing assay achieved consistent results, which depicted the suppressive effect of FDX1 on the invasiveness of tumor cells." (PMID 36275737, 2022). "The RNA expression of FDX1 differed significantly in 25 of the 33 tumor types studied." (PMID 36226187, 2022). "In addition, regarding pathological grade, FDX1 expression was inhibited in tumour groups ranging from grades 1 to 4, and grade 4 was associated with the lowest FDX1 expression (p < 0.01, grade 3 vs. grade 4)." (PMID 36186457, 2022). "FDX1 may modulate TP73 tumor suppressor through IRP2 to regulate tumor suppression, and FDX1 may be a gene related to KIRC." (PMID 36531222, 2022). "FDX1 is highly expressed in 15 tumor types and lowly expressed in 11 tumor types." (PMID 36605188, 2022). "The lower the expression of FDX1, the higher the purity of tumor cells in some kinds of cancers." (PMID 36061184, 2022). "Besides, we also found that FDX1 showed a dysregulated expressing pattern in clinical samples, and it was an independent tumor suppressor through relevant functional assays." (PMID 36275737, 2022). "Cox’s regression revealed that the FDX1 level independently predicted prognosis; FDX1 may control immune cell infiltration of the tumor microenvironment." (PMID 36579333, 2022). "Since non-tumor-related factors may lead to death during follow-up, we analyzed the relationship between FDX1 expression and DSS in pan-cancer." (PMID 36210836, 2022). "FDX1 was downregulated in the tumor, in line with its CNV depletion." (PMID 36338763, 2022). "According to the immune infiltration, single-cell analysis, and immunotherapy analysis, FDX1 may also participate in tumor immunity regulation, nevertheless, by an unidentified mechanism." (PMID 36605188, 2022). "Higher FDX1 promoter methylation in the tumor group might account for the low FDX1 expression especially in CHOL, KIRP, PCPG, SARC, TGCT, and THCA." (PMID 36605188, 2022). "Therefore, the IHC analysis of FDX1 expression revealed that FDX1 functions in tumour progression and malignancy." (PMID 36186457, 2022). "The high expression of FDX1 may inhibit the expression of cell cycle key proteins, thereby inhibiting tumor progression." (PMID 36105937, 2022). "Several studies demonstrated that phosphorylation of FDX1 could inhibit its function, which may facilitate tumor growth." (PMID 36605188, 2022). "Therefore, we developed a nomogram model to predict survival probability rates by combining FDX1 expression and independent clinical prognostic factors (age, histological tumor grade, and pathological tumor stage)." (PMID 36292610, 2022). "Its potential molecular mechanism suggests that copper ionophores can kill ccRCC cells (with high expression of FDX1), which may become a new direction of tumor therapy with important clinical guiding significance." (PMID 36105937, 2022). "Lower expression of FDX1 in the CRGPI-high subgroup may be the reason for worse OS because of less copper-induced tumor cell death." (PMID 36177029, 2022). "We observed that FDX1 was located in the cytoplasm of tumor cells." (PMID 36620594, 2022). "Tissue microarray analysis showed decreased FDX1 expression in KIRC patients’ tumor tissues." (PMID 36605188, 2022). "Moreover, the mRNA expression levels of MAP1LC3A and FDX1 in PTC tissues were significantly lower than those in non-tumor thyroid tissues." (PMID 36333684, 2022). "In addition, in terms of tumor chemotherapy, there were few studies on the relationship between FDX1 and tumor resistance." (PMID 35991547, 2022).